MITF (melanocyte inducing transcription factor)
Diseases named in the same sentence as MITF in open-access papers (continued):
Sharing a sentence is not in itself a finding about the gene and the disease.
melanoma (continued). "Moreover, since melanoma lines were found to be differentially sensitive to MITF depletion, MITF target genes might play distinct roles in survival of individual cell lines." (PMID 23349796, 2013). "However, the MITF isoform ENST00000352241 was found to be significantly overexpressed in melanoma compared with melanocytes (FC = 3.4), whereas the transcript variants ENST00000433517 (FC = -5.6) and ENST00000472437 (FC = -3.4) were underexpressed in melanoma." (PMID 23594586, 2013). "The variable levels of MITF expression in melanoma may have important consequences." (PMID 24062982, 2013). "MITF, generally believed to play a primary role in melanocyte stem-cell proliferation and expression of a set of pigment-related genes, has been shown to be amplified in a small percentage (10 to 20%) of melanomas, and seems to confer a poor prognosis when overexpressed." (PMID 23594586, 2013). "Indeed, three different melanoma cell lines exposed to the secretome collected from melanoma cells rendered senescent by temozolomide or fotemustine displayed increased expression of Fibronectin1 while exhibiting a decrease in E-Cadherin and MITF protein level." (PMID 24344100, 2013). "Therefore, it has been demonstrated that some miRNAs are involved with MITF expression in melanoma." (PMID 21860617, 2012). "Moreover, MITF continued expression seems to be essential to melanoma proliferation and survival." (PMID 21860617, 2012). "To investigate whether MiTF confers to a survival advantage in other melanoma cell lines, we exposed different melanoma cell lines with different MiTF accumulation levels to 3 mJ/cm2 of UVC and examined the cell survival 24 hours later by Propidium Iodide staining and FACS analysis." (PMID 20701798, 2010). "Therefore, MITF or MITF isoforms have the potential of being an important biomarker for melanoma." (PMID 20163701, 2010). "The novel isoform MITF-MDel was widely expressed in melanocytes, melanoma cell lines and tissues, but almost undetectable in non-melanoma cell lines or PBMC from healthy donors, and may serve as a potential candidate biomarker for diagnostic and follow-up purposes in melanoma." (PMID 20163701, 2010). "We found that MITF-Mdel was widely expressed in normal human melanocytes and melanoma cell lines as well as primary melanoma tissues, but was almost undetectable in non-melanoma cancer cell lines and pheriperal blood mononuclear cell (PBMC) from healthy donors." (PMID 20163701, 2010). "Therefore, high levels of MITF expression in primary melanoma could confer either a survival advantage or potential for terminal melanocytic differentiation." (PMID 22545195, 2010). "Therefore, MITF-Mdel seems to be a common isoform in melanoma." (PMID 20163701, 2010). "Hence we used melanocytes and representative melanoma lines to assess mechanisms underlying positive or negative regulation of MITF." (PMID 21203491, 2010). "Surprisingly, tumor suppression assays fail to generate ‘muscle-resistant’ melanoma tumor cells such that cells subject to multiple rounds of selection remain sensitive to the growth suppression effects exerted by muscle, and is accompanied by down-regulation of the transcription factor MiTF." (PMID 20174581, 2010). "Considering the hypothesis that MITF has to be upregulated in early melanoma development and subsequently downregulated when the tumour becomes invasive, the interplay between miR-137 and miR-182, and possibly some other miRNAs, may have a key role in the MITF regulating network." (PMID 19638982, 2009).
melanoma (continued). "By contrast, in cutaneous melanoma, whether superficial spreading melanoma or recurrent dermal melanoma, MITF+ fusiform dermal cells as well as dermal nest of melanocytic cells displayed a strong RACK1 cytoplasmic signal which was homogeneous over the whole lesion (F respectively)." (PMID 18442364, 2008). "Since many of the known MITF targets are represented in the Met library, this collection may contain novel MITF targets and co-regulated genes whose identification will probably contribute to shed light on the MITF participation in melanoma development." (PMID 18211678, 2008). "In vitro, hAAT upregulated melanocytic differentiation markers (MITF, TYR, PMEL, MART-1) and increased melanin production in murine and human melanoma lines, suggesting enhanced tumor immunogenicity." (PMID 41594664, 2026). "By controlling inflammatory cytokine production and modifying the tumor’s immune profile, MITF contributes to a TME that is less responsive to immunotherapy, reducing the effectiveness of ICIs in melanoma treatment." (PMID 40872475, 2025). "Their results not only support the use of a multi-genes panel test in familial melanoma, but also suggests a pivotal role of BAP1 and MITF genes." (PMID 40869905, 2025). "The correlation between MITF and RRAGD and FNIP2 mRNA expression was reproduced using The Cancer Genome Atlas (TCGA) melanoma cohort." (PMID 41275493, 2025). "For example, recent evidence suggests that lymph node metastasis require a metabolic shift towards FAO mediated by MITF, a transcription factor, in MYC+ melanoma." (PMID 40376583, 2025). "Consistent with previous observations in melanoma, in TCGA melanoma cohort, TFE3 mRNA was inversely correlated with MITF, while a moderate anti-correlation was also noted between MITF and TFEB." (PMID 41275493, 2025). "The results demonstrate that human DANCR is a MITF and c-MYC regulated lncRNA oncogene that promotes melanoma cell proliferation and migration and that melanoma patients with high DANCR expression have significantly decreased survival rates." (PMID 41336739, 2025). "SPEF significantly suppressed the elevated levels of MITF, tyrosinase, TRP1, and TRP2 expressions in α-MSH-stimulated melanoma cells." (PMID 40003988, 2025). "When MITF is upregulated in response to BRAF/MEK inhibition, it promotes cell survival, differentiation, and metabolic adaptations that enable melanoma cells to escape drug-induced cell death." (PMID 40872623, 2025). "In the same PLN74 cell line, guadecitabine treatment strongly downmodulated expression of three differentiation proteins (MITF, GP100/PMEL, MART-1), as evaluated by quantitative digital pathology on melanoma cell cytospins." (PMID 40682094, 2025). "In the present study, we found that CPEO not only inhibited UVA-induced α-MSH in keratinocytes but also downregulated melanogenesis-related molecules (MITF, tyrosinase, TRP-1, TRP-2) and melanin production in B16BL6 melanoma cells." (PMID 41304724, 2025). "Molecular parallels between COM and human melanoma, particularly MAPK pathway alterations and genes like BRAF, NRAS, MITF, and NF1, further support this study’s relevance." (PMID 40647405, 2025). "In transdifferentiated A375 cells the melanoma markers MKI67, MITF, S100A4, S100A10, MMP2 and MMP9 were significantly downregulated." (PMID 40715046, 2025). "MITF has exhibited equal or higher sensitivity and specificity than HMB-45 in the diagnosis of desmoplastic melanoma.In melanoma metastases, MITF expression is maintained in 23% to 88% of cases." (PMID 40507250, 2025). "Similar inhibition of melanin production and decreased expression of tyrosinase protein and MITF mRNA and protein were also confirmed in MNT‐1 human melanoma cells." (PMID 40524653, 2025). "Transcriptome analysis of HOXA1 endogenous melanoma cells revealed upregulation of TGF-β signaling and downregulation of melanocyte-inducing transcription factor (MITF)." (PMID 39858044, 2025).
melanoma (continued). "Here, we show that SETD6 binds and methylates BRD4 at K99 in melanoma cells to modulate the genomic distribution of BRD4 and MITF, and that BRD4 binds to MITF in vitro and in cells." (PMID 40809945, 2025). "In melanoma cell cultures and tumor samples, SOX10/MITF expression was found to correlate with and drive RNF125 transcription." (PMID 40872623, 2025). "Although MITF-low/AXL-high melanoma subtypes are known to display invasive phenotypes, our data suggest that FRA1 acts independently of direct MITF regulation." (PMID 41286309, 2025). "Our findings on MITF and NF1 further suggest that certain COM subtypes share mechanisms with human melanomas." (PMID 40647405, 2025). "Western blot analysis showed that EUE treatment under 1.5 mM H2O2 stress increased the expression of MITF, TYR, β-catenin, GSK-3β, p-GSK-3β, and Wnt-5a in B16 melanoma cells." (PMID 41496855, 2025). "Molecular confirmation is mandatory for this kind of neoplasm and the main differential diagnoses are with cellular blue naevus, melanoma, CCS, PEComa, and also MITF::CREM tumor." (PMID 40004764, 2025). "In melanoma, BRAF inhibition was shown to up-regulate oxidative phosphorylation through increased PGC1α and MITF expression." (PMID 40950224, 2025). "Other melanoma-specific markers such as human melanoma black 45 (HMB45), tyrosinase, MART-1/Melan-A, melanocyte-inducing transcription factor (MITF), and sex-determining region Y-box 10 (SOX10), aid in melanoma diagnosis." (PMID 40177537, 2025). "Fisetin treatment of melanoma cells resulted in a 2-fold increase in JNK phosphorylation, which promotes MITF degradation." (PMID 41373883, 2025). "In melanoma, ATF2 downregulation upregulates MITF via SOX10, transforming melanoma into a metastatic phenotype." (PMID 40458894, 2025). "Somatic mutations in SOX10 occur in early-stage melanoma, with SOX10 upregulating MITF, MET, and Nestin expression in melanoma and responding to Wnt signals." (PMID 41012776, 2025). "In our findings, fisetin treatment in both melanoma cells and α-MSH-stimulated melanoma cells induces JNK phosphorylation, providing a supportive pathway for MITF degradation and consequent suppression of melanin production." (PMID 41373883, 2025). "To test if DANCR is directly regulated by MITF and c-MYC in melanoma we depleted these two transcription factors in multiple human melanoma cell lines using siRNA transfection and measured changes in gene expression using RT-qPCR." (PMID 41336739, 2025). "Honokiol inhibited melanoma growth and metastasis, induced CHOP activation in ER stress, and reduced the expression of MITF, β-catenin, and CDK2 in melanoma tissues (in vitro, in vivo)." (PMID 40943669, 2025). "The high expression of MITF, β-catenin, and CDK2 indicates that honokiol is an efficient melanoma inhibitor." (PMID 40943669, 2025). "The melanocytic gene set is driven by the transcription factor MITF, which enhanced the levels of the tumor suppressor and translation inhibitor REDD2 in the TTD melanoma cells, where it antagonized proliferation." (PMID 40918647, 2025). "Epigenetic alterations further influence this resistance landscape, with methylation‐mediated repression of both MITF and SOX10 promoting melanoma dedifferentiation and consequent therapy resistance." (PMID 40458894, 2025). "YAP/TAZ-induced differentiation of melanoma cells occurs through a transcriptional interaction with PAX3 (Paired box 3), which activates MITF gene expression in these cells." (PMID 40399946, 2025). "In melanoma cells, PACAP addition resulted in a slight increase in MITF expression and a more pronounced immune signal in both of cytoplasm and the nucleus, while melanocytes did not respond in this way." (PMID 41465475, 2025). "Central to this axis are MITF and AXL, which act as antagonistic regulators of melanoma cell fate and therapy response." (PMID 41465101, 2025).
melanoma (continued). "Single‐cell studies reveal heterogeneity in MITF and SOX10 expression, correlating with distinct phenotypes in primary melanoma." (PMID 40458894, 2025). "By qPCR for two markers of differentiated melanomas (MITF and PMEL) we identified MITF/PMELHI, MITF/PMELINT and MITF/PMELLO cell lines." (PMID 40682094, 2025). "However, in melanoma cell lines LB2259-MEL and CP50-MEL treated with IL-1β, IL-1β might reduce the expression of MITF through the NF-κB and JNK pathways, and this reduction is associated with the expression of the IL-1 receptor type I (IL-1RI) gene in melanoma cells." (PMID 39689154, 2025). "SOX family members are common PAX protein co-factors; in melanocytes and melanoma, PAX3 interacts with SOX10 and drives a number of downstream genes, such as MITF, MET, and RET." (PMID 40428399, 2025). "Our data suggest that BRD4 binds MITF in melanoma cells and that this interaction is dependent on both SETD6-mediated methylation of BRD4 and MITF acetylation." (PMID 40809945, 2025). "In melanoma, BRD4 is overexpressed and essential for tumor growth in vivo and interacts with MITF to regulate the expression of genes important for melanin synthesis in melanocytes." (PMID 40809945, 2025). "In B16F10 mouse melanoma cells, morin enhanced the phosphorylation of ERK and p38 to improve the expression of TRP‐1, TRP‐2 and MITF, which regulates the synthesis of melanin." (PMID 40457938, 2025). "For P1, clusters enriched in ER lumen-associated proteins (CIP2A, OSMR, WWTR1), inflammasome-related proteins, and melanoma-specific proteins (CCND1, MITF, MLANA, NOTCH1) were notable." (PMID 40669378, 2025). "Histological markers used to diagnose melanoma are: S100 protein, HMB45, Melan-A, Tyrosinase, MITF and Vimentin." (PMID 39862670, 2025). "MITF and c-MYC, key melanoma transcription factors, regulate human DANCR expression and melanoma patients with high DANCR display significantly decreased survival." (PMID 41336739, 2025). "In melanoma cells (B16 murine melanoma cell line), TYR is co-expressed with TYRP1 or TYRP2 under the regulation of MITF." (PMID 41515356, 2025). "Here, we reveal the functional specialization of MITF, TFE3, and TFEB and their impact on melanoma progression." (PMID 41275493, 2025). "Five hub genes including CXCL11, ICAM1, LEF1, MITF, and STAT1 were identified, SUZ12, SOX2, TCF3, NANOG, and SMAD4 were determined as the most significant TFs in metastatic-melanoma." (PMID 39820173, 2025). "Drug-repositioning approaches with quinacrine and methylbenzethonium were shown to inhibit MITF epigenetically, restore APAF-1 activity, and resensitize resistant melanomas to MAPKi." (PMID 41465101, 2025). "Of importance, we also observed that MITF and ZFR are both down-regulated in two independent datasets of bulk RNA-seq data from melanoma biopsies sequenced before (Pre) or after development of resistance (PD or PROG) to targeted therapies." (PMID 38472212, 2024). "We then mimicked the melanoma cell states identified by the Visium sequencing using mIF antibodies for SOX10, MITF, B2M and NGFR." (PMID 38594286, 2024). "Abundance of AXL+ or MITF+ melanoma cells, or AXL/MITF-double-positive cells, showed a weak inverse correlation with the presence of CD8+ lymphocytes." (PMID 39697983, 2024). "The most mutated genes, which are associated with the development of resistance to targeted therapy in melanoma include CDKN2A, RB1, PIK3CA, AKT3, HOXD8, PAX5, MAP3K8, and MITF." (PMID 38275910, 2024). "Our scRNAseq data confirmed the presence of at least two distinct melanoma transcriptional signatures identified by the expression of AXL and MITF." (PMID 39697983, 2024). "Our data demonstrate that the proportion of MITF+ melanoma cells is significantly decreased upon immunotherapy, while AXL+ melanoma cells seem to be more resistant." (PMID 39697983, 2024). "In melanomas treated with BRAF and MEK inhibitors, PAX3 and MITF expression increases and appears to contribute to the early drug tolerance state." (PMID 38473380, 2024).
melanoma (continued). "The anti-melanogenic effects of B. alba were mediated through the inhibition of the regulator gene MITF and the downregulation of pigmentary genes, such as TYR, TRP-1, and DCT, in the human melanoma cells exposed to cAMP stimulator IBMX." (PMID 39335872, 2024). "Our data provide a new concept of how a small GTPase, Rab7a affects cancer/melanoma hallmarks by controlling the activity of the endolysosomal cation channel TPC2 with effects on GSK3β degradation and thus β-Catenin and MITF levels." (PMID 39562548, 2024). "Specifically, overexpression or exogenous treatment has been shown to decrease the expression of MITF, TYR, TYP1, and TYP2 and reduce the melanin production in melanoma cells or melanocytes." (PMID 39000342, 2024). "For instance, TYRP1 transcript levels fluctuate independently of MITF in patient-derived melanoma cells and in the SK-MEL-19 human melanoma cell line." (PMID 39228400, 2024). "Calycosin significantly inhibited the expression of melanin-related genes (including MITF, TYR, and TRP-1) in B2F16 melanoma cells to regulate MSH-induced melanogenesis." (PMID 38586368, 2024). "Currently, the main markers that are used for the diagnosis and detection of melanoma are S100, HMB-45, Melan A, MITF, SOX 10, microRNA, exosomes, and Melanoma-Inhibiting Activity (MIA)." (PMID 39319051, 2024). "FBXW7 also inhibits the MITF/PGC-1α pathway, thereby suppressing melanoma cell proliferation relying on mitochondrial oxidative metabolism." (PMID 39213172, 2024). "Downstream Nrf2 signaling regulates MITF activity and EGFR expression, thus highlighting the crosstalk between intracellular communication and oxidative stress management in melanoma." (PMID 39519202, 2024). "Altogether these results demonstrate that miR-579-3p is able to stabilize MITF protein and to induce its own transcription in a positive feedback regulatory loop by targeting BRAF-V600-MAPK signaling in melanoma cells." (PMID 38472212, 2024). "Altogether these findings suggest that miR-579-3p/MITF interplay potentially governs the balance between proliferation, senescence and resistance to therapies in BRAF-mutant melanomas." (PMID 38472212, 2024). "Specifically, MITF, the transcription factor known to sustain the expression of ABCB5, is highly expressed in differentiated melanoma cells and this correlates with high levels of ABCB5." (PMID 39199632, 2024). "In particular, the response of MITF- and/or AXL-expressing melanoma cells to current immunotherapies was investigated, as well as their association with immunological pressure from tumor-infiltrating lymphocytes." (PMID 39697983, 2024). "Generally, melanoma lines, which showed reduced proliferation and invasion after either TPC2 or Rab7a KD expressed higher levels of MITF." (PMID 39562548, 2024). "The pipeline identified variation in known germline melanoma genes POT1, MITF and BAP1 in 4 out of 13 families (31%)." (PMID 38866901, 2024). "They repress the MITF expression, reduce the cell growth, and inhibit the TYR activity in human melanoma cells." (PMID 39000342, 2024). "A recent study examining transcriptomes from melanoma cells found EMT/invasive states and NCSC-like cells differ in their genetic backgrounds, but both exist with low levels of MITF." (PMID 38426087, 2024). "Prior research has underscored the pivotal role of MITF in transcriptionally regulating melanogenic enzymes, including tyrosinase, TRP-1, and TRP-2, thereby modulating melanogenesis in melanoma cells." (PMID 38794376, 2024). "Cytosolic and mitochondrial ROS levels were measured by DCFDA and Mitosox fluorescent dyes, respectively, using flow cytometry before/after knockdown of MITF in UACC257 and SKMEL5 melanoma cells." (PMID 39277608, 2024). "As expected, TNF decreased the gene expression of MITF and its target genes MLANA, DCT and TYR, and, conversely, increased the expression of the stemness factor NGFR in 451Lu melanoma cells." (PMID 39136013, 2024).